TNF (tumor necrosis factor)
Diseases named in the same sentence as TNF in open-access papers (continued):
Sharing a sentence is not in itself a finding about the gene and the disease.
tumor (continued). "On the one hand, TNF-α exerts an antitumor effect by inducing apoptosis in malignant cells, raising the concern that inhibiting this cytokine may impair tumor surveillance, potentially causing the recurrence or rapid progression of cancer." (PMID 40227584, 2025). "while tumor immune evasion is attributed to the loss of TNF sensitivity." (PMID 40483533, 2025). "Mast cell activation and mediator release have been documented in ARDS and COVID-19-associated lung injury, while in some lung tumors, released TNF-α and other mediators may influence tumor behavior and the tumor microenvironment." (PMID 40807076, 2025). "According to network pharmacology and molecular docking, HSP90AA1 and TNF‐α may be implicated in the action of NF against the wasting of muscles in tumour‐bearing mice." (PMID 40170230, 2025). "TNF acts on vascular endothelial cells, causing endothelial cell damage, vascular dysfunction and injury, thrombosis, and local blood flow blockade of the tumor tissue." (PMID 40136649, 2025). "IL-6 and TNF-α are central activators of NF-κB, driving angiogenesis, epithelial–mesenchymal transition, and resistance to apoptosis, while IL-1β has been implicated in promoting immunosuppression and metastatic spread within the tumor microenvironment." (PMID 41020906, 2025). "In the immune system, MAGI2-AS3 could modulate genes related to immune cell activation and cytokine production, such as IL-6 and TNF-α, which are crucial in tumor-associated inflammation." (PMID 40687762, 2025). "Among these, IL-2 and TNF-α are especially relevant for T cell expansion and anti-tumor immunity, while IL-4 and IL-10, linked to Th2 responses, may play a lesser role in MM immune surveillance." (PMID 40948764, 2025). "Indirect mechanisms involve tumor-associated inflammation and immune dysregulation: The tumor microenvironment secretes pro-inflammatory factors (e.g., IL-8, TNF-α), inducing bronchial mucosal edema and mucus hypersecretion, which leads to mucus plug formation and exacerbates airway obstruction." (PMID 41163849, 2025). "Elevated circulating monocytes serve as precursors of tumor-associated macrophages (TAMs), which accumulate within the tumor microenvironment and are sustained by inflammatory mediators such as IL-6, tumor necrosis factor-α (TNF-α), and prostaglandin E2 (PGE2)." (PMID 41487591, 2025). "However, elevated levels of tumor-promoting cytokines, including TNFα and IL6, were associated with poorer PFS, emphasizing the need for precise modulation of immune responses to optimize clinical outcomes." (PMID 40433369, 2025). "Specifically, tumor-associated macrophages (TAMs) create an immunosuppressive milieu through the production of a plethora of paracrine factors (IL-6, IL-12, TNF-alpha, TGF-beta, CCL1, CCL18) promoting the acquisition by CSCs of a stem-like, invasive and metastatic phenotype." (PMID 39981232, 2025). "Numerous studies have shown that VN stimulation can attenuate the sympathetic stress response and inhibit tumor growth, which may be associated with a reduction in plasma TNF-α levels." (PMID 40165090, 2025). "Thus, CV increases the production of TNF-α, IL-6, and other proinflammatory cytokines, promoting M1 polarization of tumor-associated macrophages (TAMs) and reducing angiogenic factors such as VEGF and MCP-1." (PMID 41150756, 2025). "TNF-α has also been associated with the growth, proliferation, and immune evasion of tumour cells." (PMID 39911325, 2025). "Moreover, dysregulated expression of TNF-α, IL-6, and IL-1β was closely associated with altered cellular microenvironments and tumor pathological progression." (PMID 41323840, 2025). "TPA is a skin irritant, the action of which causes keratinocytes and epidermal dendritic cells to produce inflammatory molecules such as TNF-α, causing acute inflammation with the recruitment of immune cells, namely, neutrophils, macrophages, and mast cells, from the skin tissue." (PMID 40219189, 2025).
tumor (continued). "While TNF-α is a proinflammatory cytokine, crucial for promoting a strong and functional type 1 anti-tumor immune response, IL-33 and IL-4 are associated with immunosuppression and tumor promotion." (PMID 40943444, 2025). "P.g. may contribute to OSCC recurrence by upregulating DOK3 in tumor-associated macrophages, activating TNF and MAPK signaling." (PMID 40924302, 2025). "Furthermore, CRP is an acute-phase protein influenced by IL-6 and TNF-α, linked to tumor aggressiveness and cachexia." (PMID 40786260, 2025). "Furthermore, we identified a significant increase in interleukins and tumour necrosis factors, including IL‐1a, IL‐1b, IL‐6, IL‐17C, IL‐32, IL‐36G and TNF, along with its associated enzyme." (PMID 39865778, 2025). "For example, tumour‐associated macrophages and other immune cells may release TNFα in response to tumour growth and this increase in systemic inflammation may be detectable by ELISA in brain tissue." (PMID 40172096, 2025). "Additionally, the loss of the transcription factor CBFβ in tumor cells disrupts zinc homeostasis pathways, further impairing their responsiveness to TNF-dependent cytotoxicity." (PMID 40390089, 2025). "ESCC tumor cells and surrounding stromal cells (e.g., tumor-associated macrophages, TAMs) can continuously secrete large amounts of pro-inflammatory cytokines (e.g., IL-6, IL-8, TNF-α) and growth factors (e.g., VEGF)." (PMID 41141695, 2025). "Moreover, catumaxomab binds to CD3 on T cells, triggering their activation and proliferation, causing tumor-killing molecules such as tumor necrosis factor-alpha (TNF-α), interferon-gamma (IFN-γ), perforin, and granzyme B to be released." (PMID 41275209, 2025). "Indeed, increased expression of RELA mRNA, encoding p65 protein, and the activation of TNF-α-mediated NF-κB signaling are observed in GBM-formed tumor masses." (PMID 40288646, 2025). "In this study, 24 h after central nervous system (CNS) ischemia, the concomitant inflammatory cascade response with elevated levels of tumor necrosis caused systemic peaks of TNF-α, IL-1β, and IL-6, and pre-administration of GJC-CDs reduced the levels of related inflammatory factors." (PMID 40573265, 2025). "In low concentrations, TNF-α is implicated in promotion of angiogenesis and facilitating tumor cell metastasis, whereas elevated levels of TNF-α may have antitumor effects." (PMID 40313970, 2025). "This discrepancy may suggest a more prominent role for IL-6 in tumor-associated inflammation than TNF-α." (PMID 41155372, 2025). "While elevated TNF-α is typically associated with inflammation, its context-dependent role in promoting tumor cell apoptosis may explain its concurrent upregulation alongside enhanced cytotoxicity in viability assays." (PMID 41401147, 2025). "However, the associations of TNF-α gene SNPs with BC susceptibility, prognosis, and tumor characteristics are still debated." (PMID 39570546, 2025). "Additionally, genes, associated with inflammasome and cell death including tumor suppressive TNF signaling pathways were upregulated in the samples treated with NT GSDMD + IL-1β + IL-18." (PMID 39737979, 2024). "Furthermore, pro-inflammatory diets are implicated in indirectly boosting the production of tumor-promoting cytokines like IL-6 and TNF." (PMID 38992637, 2024). "To test whether the tumor-associated IFNγ and TNFα can stimulate the production of G-CSF, we treated MSCs with the two cytokines." (PMID 38690266, 2024). "Intratumoral CD8+ cytotoxic T cells play an important role in tumor-killing activity by interacting with tumor antigens and causing direct or indirect cell lysis mediated by cytokines such as interferon-γ, tumor necrosis factor α (TNFα), and granulocyte-macrophage colony-stimulating factor (GM-CSF)." (PMID 39769460, 2024). "Previously, TNF-α was implicated in suppressing tumor angiogenesis; however, recent investigations suggest a more nuanced role, revealing its potential for pro-angiogenic activity within the tumor microenvironment." (PMID 39450177, 2024).
tumor (continued). "In addition, Cytokines like IL-2, IL-12, IL-23, and TNF-α can be produced by tumor-associated macrophages, dendritic cells, or CD4+ T cells, all of which are paired with CTL, NK cells, Th17 cells proliferation." (PMID 38887597, 2024). "In the context of OSCC, some reports have demonstrated that several cytokines, particularly TNF-α, promote tumor progression by upregulating the genes associated with neutrophil recruitment and invasion, as well as IL-10, which has been associated with a more aggressive OSCC phenotype." (PMID 39204206, 2024). "While Fas-ligand and to a much lesser extend TNFα, due to the requirement of protein synthesis or transcription inhibitors, are efficient in killing a variety of tumour cells, these ligands cause significant damage to normal tissues that result in life-threatening toxicities." (PMID 38534365, 2024). "This study aimed to determine whether macrophages secrete tumor-associated factors, such as TNF-α and IL-6, when co-cultured with cancer cells treated with TiO2@OMV carriers and subjected to radiation therapy." (PMID 39728581, 2024). "After IFN-γ stimulation, Tumor-associated macrophages (TAMs) polarize in M1-like, with antigens-presenting function to lymphocytes and pro-inflammatory cytokines production such as IL-12, IL-1, TNF-α." (PMID 38799450, 2024). "Additionally, it has been shown that tumor-associated macrophages can contribute to the growth of encountered cancer cells by promoting their glycolysis through TNFα." (PMID 38216787, 2024). "Tumor cell killing is associated with increased IL-2, TNF-α and/or IFN-γ secretion." (PMID 38582787, 2024). "Tc1s secrete IFN-γ and TNF-α and feature significant anti-tumour effects causing cell lysis." (PMID 38920685, 2024). "Following oncolytic tumor cell death, the release of cell damage-associated molecular patterns (DAMPs), tumor antigens, and cytokines such as type I interferons and TNF-α activates innate immune responses and tumor-specific adaptive immune responses to further eliminate tumor cells." (PMID 38679698, 2024). "Growth factors including TGFβ and TNFα, which can be produced by transformed neoplastic cells or by tumor-associated microglia and macrophages, are reported to drive proneural-to-mesenchymal transition (PMT) via transcription factors including SMADs, ZEB1, NF-κB, STAT3, C/EBPβ, and TAZ." (PMID 38337036, 2024). "In fact, elevated levels of TNF-α released by ASCs establish a positive feedback loop and further stimulate ASCs to secrete multiple cytokines and chemokines that are significantly associated with enhanced metastasis and tumor growth." (PMID 39123496, 2024). "Additionally, CDK9i evoked the expression of these genes while decreasing those associated with inflammation and tumor killing (e.g., TNF and IL1B)." (PMID 39254172, 2024). "The monocyte-macrophages were associated with various tumor-related signaling pathways, such as NF-kappa B signaling pathway, TNF signaling pathway, NOD-like receptor signaling pathway, Toll-like receptor signaling pathway, Chemokine signaling pathway, IL-17 signaling pathway." (PMID 38529274, 2024). "Currently, TNF is known to be a classic pro-inflammatory cytokine that also plays an important role in the development of inflammatory autoimmune diseases such as rheumatoid arthritis, sepsis and inflammation-associated proliferation of tumor cells." (PMID 38612709, 2024). "In contrast, macrophages TLR4 wild-type adoptive transferred in TLR4-deficient mice bearing tumor, showed a significantly higher NF-κB activity, enhanced release of inflammatory factors such as TNF-α and VEGF, thus prompting an increased NF-κB activity in tumor cells and tumor growth in vivo." (PMID 38397187, 2024). "The pro-inflammatory cytokine TNF-α may be secreted by stromal cells, tumor-associated macrophages, and by cancer cells, indicating a prominent role in the tumor microenvironment (TME)." (PMID 38698424, 2024).
tumor (continued). "Mechanistically, Yap deletion caused the upregulation of beta-lymphocyte-induced maturation protein 1 (BLIMP1), which is an inducer of terminal T-cell differentiation, and elevated the production of interferon gamma (IFNγ) and tumor necrosis factor alpha (TNFα) which cause anti-tumor effects." (PMID 38538573, 2024). "Besides the expression of IFNγ, tumor necrosis factor (TNF)-α and granzyme B was elevated, exhibiting that tumor-infiltrating Blimp1-deficient Tregs were reprogrammed." (PMID 39227959, 2024). "The upregulation of a host of genes involved in antigen processing and presentation, such as β2m, Calr, Tapbp, and others, in TNFR1-deficient mice suggests that TNF may suppress this ability in tumor-infiltrating DC2s." (PMID 39178856, 2024). "Variants in genes like CTLA-4, ERCC3, and TNF-α might impact immune regulation and inflammatory responses, crucial in tumor microenvironment dynamics." (PMID 38360742, 2024). "TA-pDCs recovered in ascites from ovarian tumor patients secreted the proangiogenetic factors CXCL8 and TNF-α, while in non-small cell lung cancer patients, tumor-infiltrating pDCs were reported to cause tumor proliferation via the pro-angiogenic effects of IL-1α." (PMID 38504978, 2024). "TNF-α targets not only cancer cells, but also tumor-associated vasculature." (PMID 38698424, 2024). "Similarly, IL-18 and TNF-α, both implicated in tumour growth and angiogenesis, point to a complex network of cytokine interactions driving the progression from chronic inflammation to cancer." (PMID 38561502, 2024). "In order to mimic a pathological muscle microenvironment, C2C12 myotubes were exposed to the pro-inflammatory cytokine TNF-α or to a medium conditioned by C26 cells (CM-C26), a well-characterized tumor known for its ability to cause cachexia when implanted into a host mouse." (PMID 38732549, 2024). "Despite the expression of these exhaustion markers, antigen-specific intratumoral CD8 T cells were able to secrete IFNγ, TNFα, and Granzyme B upon ex vivo restimulation, showing that they maintained their functionality, which was associated with tumor regression." (PMID 38893156, 2024). "Thus, we detected which signaling pathway was associated with the ability of TNF-α and IL-1β to regulate tumor cells." (PMID 39726047, 2024). "TRIM8 could also mediate K63-linked ubiquitination of TAK1, hence activating TNF-α, IL-1β and NF-κB signaling, which cooperatively promote malignant phenotypes of tumor cells." (PMID 38879600, 2024). "TNF-α production is associated with apoptosis-induced tumor cell death." (PMID 38974834, 2024). "GP-NMB antibodies, αCD40 and TNFα together activate DCs and induce FcγR-dependent tumor regression with activated effector/memory T-cell infiltration, suggesting that tumor-reactive T cells targeting tumor-associated antigens that are not widely expressed alloantigens are needed." (PMID 38461238, 2024). "There is a type of antigen-presenting cells (APCs), Dendritic cells (DCs) that could inhibit primary tumors and cause tumor regression by producing a broad range of mediators that activate IL-1 and TNF-α genes." (PMID 37505298, 2024). "Besides, TNF-α stimulated Erk activation, which causes increased production of this cytokine by tumor cells." (PMID 37507626, 2024). "Through our integrated clinical-biomarker–immunologic analyses derived from a diverse, pan-tumor cohort, we found that early increases in Th17 (IL-6, IL-17f), type 2 (IL-5, IL-13, IL-25), and type 1 (TNF-α) cytokines were associated with the development of grade ≥ 2 irAEs." (PMID 39403935, 2024). "Moreover, a significant production of cytokines TNF-α and IL-10 was noticed in the Cutibacterium-treated cells, further indicating a close association of this bacterium with tumor activities." (PMID 39201629, 2024). "TNF and IL-6 can cause disordered cytokine regulation and promote tumor inflammation." (PMID 37077811, 2023).
tumor (continued). "Additionally, TNFα can cause a dedifferentiation of tumor cells, leading to loss of neoantigens and an increase in PD-L1 expression." (PMID 37461742, 2023). "High levels of expression of GZMB and FASL (encoding Granzyme B and Fas ligand) but low levels of IFNG and TNF (encoding Interferon-γ and TNF-α) in these exhausted-like T cells are suggestive of an altered cytotoxic profile but remaining capacity for tumor cell killing." (PMID 36609566, 2023). "In this model, CER-1236 not only mobilize proinflammatory (IFN-γ, TNF-α, chemokines) and cytotoxic functions but also process tumor-associated antigens to generate tumor antigen-specific T cells, and therefore overcome antigen presentation defects in the tumor microenvironment." (PMID 37194236, 2023). "Pro-inflammatory bacteria stimulate the production of cytokines and chemokines, such as IL-6, IL-8, IL-1b, and TNF-α, which recruit and activate various immune cells, including tumor-associated macrophages (TAMs), T cells, and myeloid-derived suppressor cells (MDSCs)." (PMID 37760801, 2023). "Their study indicated that dietary tryptophan or indoles could activate the AhR of tumor-associated macrophages to reduce the accumulation of TNFα+IFNγ+CD8+ T cells, impairing the anti-tumor immune response in PDAC." (PMID 38169949, 2023). "Meanwhile, EC tumor cells can release TNF-α causing DNA damage and abnormal cell repair." (PMID 37927462, 2023). "Moreover, residual tumor-promoting activity in the skin of TNF-α−/− mice was associated with induction of IL-1α and IL-1β gene expressions." (PMID 37097392, 2023). "In a tumour setting, T cells become exhausted due to chronic antigen exposure leading to reduced effector function [loss of interleukin-2 (IL-2), tumour necrosis factor alpha (TNF-α) and Interferon-gamma (IFN-γ) production]." (PMID 37554723, 2023). "Complementing their cytotoxic capabilities, γδ T cells can also secrete cytokines IFN-γ and TNF-α, jointly suppressing tumor-associated angiogenesis.In some hematologic tumors, γδ T cells have been found to be capable of immunosurveillance by NK-like mechanisms." (PMID 38077392, 2023). "As a result, administering the delivery system combined with plasmid DNA encoding tumor necrosis factor alpha (TNFα) resulted in rapid and sustained tumor regression for 40 days, during which all A431 tumor-bearing mice survived (90% of which had a complete response) and were well-tolerated." (PMID 37242604, 2023). "Additionally, the systemic administration of Tf-PEG-PEI/DNA complexes encoded TNF-induced efficient tumor necrosis and inhibited tumor growth." (PMID 37958989, 2023). "In addition, PDL1 expressed by tumor cells and their related stromal cells can be stabilized by tumor necrosis factor alpha (TNF-α) and causes the suppression of antitumor immunity." (PMID 36673047, 2023). "This combination of immunotherapy retards tumor growth and prolongs the patient’s survival by rapidly inducing hemorrhagic necrosis dependent on tumor necrosis factor (TNF) production by tumor-associated myeloid cells followed by a CD8 T cell response required for tumor eradication." (PMID 37361202, 2023). "Importantly, the results of in vivo experiments show that it can significantly inhibit tumor growth by promoting tumor-associated macrophage repolarization into M1 type, releasing TNF-α and IL-6 to initiate tumor immunity." (PMID 37894410, 2023). "Monocytes were found to differentiate into tumor‐associated macrophages, which could secrete tumor necrosis factor alpha and vascular endothelial growth factor to facilitate tumor angiogenesis, inflammatory response, and metastases." (PMID 37128769, 2023). "Tumor pH gradients, hypoxia, damage-associated molecular patterns, membrane lipids, destabilizing ions, and peptides, increased matrix stiffness, and NFκB and TNFα-mediated signaling collectively generate an environment permissive for cell fusion." (PMID 37046676, 2023).